DPP6 (dipeptidyl peptidase like 6)
Diseases named in the same sentence as DPP6 in open-access papers (continued):
Sharing a sentence is not in itself a finding about the gene and the disease.
tumor (17 papers, 2012 to 2025). "Considering tumor location, it is observed that it might be associated to the expression profile of DPP6." (PMID 37372430, 2023). "The hypermethylation of DPP6 was associated with high-grade tumor in ccRCC." (PMID 35565241, 2022). "Studies have revealed that amongst the 6 identified target genes, Dpp6 and Pcdh9 were Tumor suppressor genes (TSGs) and Avpr2, Cyp4a12b, Dpp6, Gria2, Pcdh9 and Tspan11 were key tumor-related transcripts that can regulate various pathways during carcinogenesis." (PMID 35263365, 2022). "The results confirmed that methylation levels of the DPP6 promoter was significantly increased in tumor tissues compared with normal tissues." (PMID 32701143, 2020). "The results of BSP revealed that the number of methylated CG sites in the DPP6 promoter was greater in tumor samples than in normal samples (7.43 vs. 2.78, P<0.001)." (PMID 32701143, 2020). "The methylation level of the DPP6 promoter was moderately effective at distinguishing tumor from normal samples (area under ROC curve (AUC) = 0.74, P<0.001)." (PMID 32701143, 2020). "The tracer displays high specificity for DPP6 and its in vivo properties were validated in mice xenografted with either human insulin secreting cells or a neuronal derived tumour that spontaneously expresses DPP6." (PMID 29123178, 2017). "The tracers displayed optimal in vivo specificity, with high EndoC-βH1 transplant-to-muscle and high Kelly tumour-to-blood ratios, and excellent in vivo visualization of these DPP6-expressing cells implanted either in the muscle or in the subcutaneous tissue." (PMID 29123178, 2017). "The downregulated mRMR genes for normal versus tumor samples are DPP6 and FOXJ1." (PMID 35565241, 2022). "Among the five genes in ccRCC, ATP6V0D2, DPP6, PADI1 and PLG were significantly associated with AJCC-stage (p < 0.05); ATP6V0D2, C9orf135, DPP6 and PLG were significantly associated with nodal metastasis (p < 0.05); ATP6V0D2, DPP6 and PLG were significantly associated with tumor grade (p < 0.05)." (PMID 32002016, 2020). "Importantly the high tumour-to-background levels of the lead anti-DPP6 nanobody in the dissection analyses were translated into a clear visualization of tumours in fused SPECT/CT images." (PMID 29123178, 2017). "Mainly, the expression profiles of DPP6 and GABRB2 in tumor cases seem to be clearly related with most of the clinical variables under study." (PMID 37372430, 2023). "However, the function of DPP6 in regulating tumor progression is unknown." (PMID 32701143, 2020). "BSP was performed focusing on the promoter regions of four potential PMDGs (DPP6, HIST1H4E, MTMR7, and ZFP28) in 72 paired tumor and adjacent normal samples of PDAC patients." (PMID 32701143, 2020). "The results confirmed that the numbers of methylated CG sites in DPP6 and MTMR7 in tumor tissues were significantly higher than in normal tissues (7.43 ± 6.12 vs. 2.78 ± 2.96, P<0.001; 45.95 ± 16.68 vs. 31.36 ± 16.90, P<0.001)." (PMID 32701143, 2020). "Apropos tumor stage, it is seen that GABRB2, DPP6 and PTGFR might have some relation with the progression of the disease." (PMID 37372430, 2023). "Moreover, several malignant phenotypes, such as tumor size, lymph node invasion, and TNM stage, were related to hypermethylation of the DPP6 promoter." (PMID 32701143, 2020). "Out of eleven genes, there was insufficient or no data for DPP6 or SEZ6L and NTSR1 in the tumor tissues for which they were identified throughout the study; thus, no comparison was possible." (PMID 35361846, 2022).
cancer (16 papers, 2012 to 2022). A tumor composed of atypical neoplastic, often pleomorphic cells that invade other tissues. "The only unequivocal “anti-cancer” cases are DPP6 in ESCA (for AP-2α) or COL4A3 in UCEC (for AP-2γ) but this cannot be concluded only on the basis of the single TF–target example." (PMID 35361846, 2022). "Six genes were found to be implicated in cancer etiology/progression/clinical outcomes with high degree of certainty: MMP1, DDX4, TRPM3, DPP6, KCNA1, and MUC17." (PMID 32625238, 2020). "Previous reports also showed regulation of Dpp6 expression by DNA methylation in some cancers." (PMID 23409053, 2013). "In addition, SPHKAP was down regulated in cancer cell lines investigated, while the expression of DPP6 and ID4 was variable among cancer cell lines." (PMID 22479372, 2012). "CNR1, DHCR24, DPP6, and MEF2C were strongly correlated with disturbances in executive functioning, episodic memory, and visuospatial functioning, which deregulate expression in multiple human cancers contributing to the antioxidant and repairing activity." (PMID 36518809, 2022).
neurological diseases (6 papers, 2021 to 2025). "The prevalence of DPP6 in these processes underscores its importance in brain function, and recent work has identified that its dysfunction is associated with host of neurological disorders." (PMID 36012450, 2022). "This review aims to summarize the associations between DPP6 and neurological diseases, offering insights as well as proposing hypotheses to elucidate the underlying mechanisms of DPP6 dysregulation." (PMID 40109277, 2025). "Based on the differential levels of DPP6 in brain derived extracellular vesicles in peripheral blood, it is possible to explore its potential as a biomarker for neurological diseases through clinical research." (PMID 40109277, 2025). "Similar to the DPP6 gene, Tang’s study found that VTI1A is mainly involved in neuronal development and neurotransmission, and mutations are likely to lead to neurological dysfunction and neurological diseases." (PMID 34684344, 2021).
neurodevelopmental disorder (5 papers, 2018 to 2021). A behavioral and cognitive disorder with onset during the developmental period that involves impaired or aberrant development of intellectual, motor, or social functions. "These terminal events impact IGF1R, CNTNAP2, and DPP6, shown to be strongly associated with neurodevelopmental disorders." (PMID 31475484, 2019). "DPP6 regulates hippocampal synaptic development and function and has been implicated in neurodevelopmental disorders that impact learning and memory." (PMID 29651237, 2018). "Clinically, the DPP6 gene has been associated with numerous developmental and intellectual disorders and neuropsychiatric pathologies but perhaps most consistently with neurodevelopmental disorders." (PMID 29651237, 2018). "DPP6 is involved in a variety of cellular pathways, including neurogenesis and neuronal excitability, and its deletion has been associated with low intelligence and neurodevelopmental disorders." (PMID 34684344, 2021). "Both WT PrPC and HRdup PrP undergo physical interactions with DPP6, a type II membrane protein that controls dendritic morphogenesis and one wherein gene disruptions link to different neurodevelopmental disorders." (PMID 29338055, 2018).
genetic diseases (1 paper, 2019). "The remaining genes, DPP6, INPP5F, CCHCR1, and CBFA2T3, are also associated with many genetic diseases." (PMID 31332212, 2019).
heart disease (1 paper, 2022). "Using these data we can hypothesize that DPP6 is involved in severe heart disease that is likely caused by gene-related atherosclerotic mechanisms." (PMID 35020748, 2022).
kidney diseases (1 paper, 2022). "We identified six genes enriched to kidney diseases and ccRCC (AR, DPP6, GNB3, IL4, SAA1, SEMA3G)." (PMID 35565241, 2022).
movement disorder (1 paper, 2014). Neurological conditions resulting in abnormal voluntary or involuntary movement, which may impact the speed, fluency, quality and ease of movement. "Mutations of DPP6 produce human disease and cause movement disorders." (PMID 24752238, 2014).
DPP6 also shares sentences with these, for which no sentence is quoted: neurodegenerative disease (4 papers); cardiac arrhythmia (2); cognitive deficits (2); cognitive diseases (2); ovarian carcinoma (2); 22q11.2 deletion syndrome (1); alcohol use disorder (1); arrhythmogenic right ventricular dysplasia/cardiomyopathy (1); autoimmune encephalitis (1); bipolar disorder (1); brain diseases (1); brain neoplasm (1); cardiomyopathy (1); congenital heart disease (1); developmental delay (1); diaphragmatic hernia (1); endometrial cancer (1); esophageal cancer (1); eye problems (1); glaucoma (1); infection (1); Klinefelter syndrome (1); learning disorder (1); leiomyoma (1); Long QT syndrome (1); lymph node metastasis (1); memory (1); Naxos disease (1); Parkinson disease (1); polymorphic ventricular tachycardia (1).
A further 7 diseases each share a sentence with DPP6 in 1 paper.